SKIC8 (SKI8 subunit of superkiller complex)
Description:
Component of the PAF1 complex (PAF1C) which has multiple functions during transcription by RNA polymerase II and is implicated in regulation of development and maintenance of embryonic stem cell pluripotency. PAF1C associates with RNA polymerase II through interaction with POLR2A CTD non-phosphorylated and 'Ser-2'- and 'Ser-5'-phosphorylated forms and is involved in transcriptional elongation, acting both independently and synergistically with TCEA1 and in cooperation with the DSIF complex and HTATSF1. PAF1C is required for transcription of Hox and Wnt target genes. PAF1C is involved in hematopoiesis and stimulates transcriptional activity of KMT2A/MLL1; it promotes leukemogenesis through association with KMT2A/MLL1-rearranged oncoproteins, such as KMT2A/MLL1-MLLT3/AF9 and KMT2A/MLL1-MLLT1/ENL. PAF1C is involved in histone modifications such as ubiquitination of histone H2B and methylation on histone H3 'Lys-4' (H3K4me3). PAF1C recruits the RNF20/40 E3 ubiquitin-protein ligase complex and the E2 enzyme UBE2A or UBE2B to chromatin which mediate monoubiquitination of 'Lys-120' of histone H2B (H2BK120ub1); UB2A/B-mediated H2B ubiquitination is proposed to be coupled to transcription. PAF1C is involved in mRNA 3' end formation probably through association with cleavage and poly(A) factors. In case of infection by influenza A strain H3N2, PAF1C associates with viral NS1 protein, thereby regulating gene transcription. Required for mono- and trimethylation on histone H3 'Lys-4' (H3K4me3), dimethylation on histone H3 'Lys-79' (H3K4me3). Required for Hox gene transcription. Also acts as a component of the SKI complex, a multiprotein complex that assists the RNA-degrading exosome during the mRNA decay and quality-control pathways. The SKI complex catalyzes mRNA extraction from 80S ribosomal complexes in the 3'-5' direction and channels mRNA to the cytosolic exosome for degradation. SKI-mediated extraction of mRNA from stalled ribosomes allow binding of the Pelota-HBS1L complex and subsequent ribosome disassembly by ABCE1 for ribosome recycling.
Synonyms: Ski8; WDR61; REC14
Tractability: Small molecule: it has a high-quality binding pocket. PROTAC: ubiquitination databases record sites on it.
Gene: Protein-coding gene on chromosome 15 (78,274,515 to 78,299,703, reverse strand). Ensembl gene ENSG00000140395.
Subcellular location: Nucleus; Cytoplasm
Subcellular location (Human Protein Atlas): Cytosol; Nucleoplasm
Pathways (Reactome):
Gene expression (Transcription): Formation of RNA Pol II elongation complex; RNA Polymerase II Pre-transcription Events; RNA Polymerase II Transcription Elongation
Chromatin organization: CHD1 and CHD2 subfamily
Disease: Dengue virus activates/modulates innate and adaptive immune responses
Metabolism of RNA: mRNA decay by 3' to 5' exoribonuclease
Metabolism of proteins: E3 ubiquitin ligases ubiquitinate target proteins
Gene Ontology:
Molecular function: protein binding
Biological process: negative regulation of myeloid cell differentiation; nuclear-transcribed mRNA catabolic process; nuclear-transcribed mRNA catabolic process, 3'-5' exonucleolytic nonsense-mediated decay; rescue of stalled ribosome; transcription elongation by RNA polymerase II
Cellular component: Cdc73/Paf1 complex; cytoplasm; cytosol; euchromatin; nucleoplasm; nucleus; Ski complex
Genetic constraint (gnomAD): Loss-of-function variants: 19 observed, 41.71 expected, observed/expected ratio (o/e) 0.46, 90% interval 0.32 to 0.67. The upper end of that interval is the gene's LOEUF score, 0.67, which puts it in group 2 of 6, group 1 being the genes least tolerant of losing a copy. Missense variants: 239 observed, 380.85 expected, observed/expected ratio (o/e) 0.63, 90% interval 0.56 to 0.7. Synonymous variants: 121 observed, 136.9 expected, observed/expected ratio (o/e) 0.88, 90% interval 0.76 to 1.03.
Homologues: Orthologues: chimpanzee SKIC8 (100% identical), pig SKIC8 (99% identical), guinea pig SKIC8 (99% identical), dog SKIC8 (98% identical), mouse Skic8 (97% identical), rat Skic8 (97% identical), macaque SKIC8 (93% identical), tropical clawed frog skic8 (86% identical), zebrafish skic8 (66% identical), Drosophila melanogaster CG3909 (55% identical), rabbit SKIC8 (52% identical), Caenorhabditis elegans F02E9.10 (15% identical), and 1 more. Paralogues in human: UTP4 (26% identical).
Diseases named in the same sentence as SKIC8 in open-access papers:
SKIC8 is named in the same sentence as 4 diseases in open-access papers, as found by Europe PMC text mining. Sharing a sentence is not in itself a finding about the gene and the disease.
SKIC8 shares sentences with these, for which no sentence is quoted: cancer (2 papers); infection (2); infertile (1); psychosis (1).